TRIM28 (tripartite motif containing 28)
Diseases named in the same sentence as TRIM28 in open-access papers (continued):
Sharing a sentence is not in itself a finding about the gene and the disease.
melanoma (23 papers, 2017 to 2026). A malignant, usually aggressive tumor composed of atypical, neoplastic melanocytes. "High TRIM28 mRNA expression is associated with the stem cell-like phenotype of melanoma cells and poor prognosis in melanoma patients." (PMID 39100077, 2024). "Using three independent datasets (SKCM TCGA, GSE65904, and GSE19234), we also demonstrated that TRIM28 upregulation is associated with a dramatically lower survival rate of melanoma patients." (PMID 33076560, 2020). "The aim of our study was to investigate the association between TRIM28 level and melanoma stemness accompanied by low antitumor immune response." (PMID 33076560, 2020). "Here, we investigated the association between TRIM28 level and melanoma stemness, and aligned it with the antitumor immune response to find the mechanism of “stemness high/immune low” melanoma phenotype acquisition." (PMID 33076560, 2020). "This suggests that the melanoma stem-like phenotype of melanoma with high TRIM28 expression may be caused, at least in part, by significant activation of c-Myc." (PMID 36756159, 2023). "TRIM28 high expression is associated with worse melanoma patient outcomes." (PMID 33076560, 2020). "Mechanistically, TRIM28 promotes the invasiveness of melanoma cells and inhibits tumor growth by negatively regulating the expression of Jun B proto-oncogene (JUNB)." (PMID 39100077, 2024). "Further research has found that TRIM28 knockdown induces the transition of melanoma from invasiveness to tumor growth." (PMID 39100077, 2024). "This relationship between TRIM28 expression and patient response was consistent in the GSE91061 melanoma cohort, where melanoma patients with low TRIM28 expression exhibited improved survival outcomes compared to those with high TRIM28 expression." (PMID 37865804, 2023). "We focus on the druggable family of bromodomain epigenetic readers and identify TRIM28 as a new regulator of melanoma plasticity." (PMID 36341538, 2023). "Melanoma with high TRIM28 expression showed less immune cell infiltration, including Cytotoxic T cells, helper T cells, B cells, macrophages, and eosinophils." (PMID 36756159, 2023). "We find that TRIM28 promotes the expression of pro‐invasive genes and that TRIM28 controls the balance between invasiveness and growth of melanoma cells." (PMID 36341538, 2023). "Melanoma tumors with high TRIM28 expression were depleted of infiltrating immune cells and are characteristic of patients with poor outcomes, while melanoma cell cultures with high expression of TRIM28 have an enhanced ability to form melanosphere." (PMID 36077272, 2022). "TRIM28 high level related to higher melanoma stemness as measured with several distinct scores and TRIM28HIGH-expressing melanoma cell lines possess the greater potential of melanosphere formation." (PMID 33076560, 2020). "TRIM28 emerged as a direct link between stem cell-like phenotype and attenuated antitumor immune response in melanoma, although further studies are needed to evaluate the direct mechanism of TRIM28-mediated stem-like phenotype acquisition." (PMID 33076560, 2020). "A significant reduction of these subpopulations that corresponds to higher TRIM28 expression was further confirmed with additional melanoma datasets." (PMID 33076560, 2020). "We analyzed the expression of TRIM28 in melanomas with low (0 or 2), medium (3 or 4), or high (5 or 6) LScores, and observed higher level of TRIM28 in low LScore melanomas (p = 0.0066);." (PMID 33076560, 2020). "Here, we analyzed the association of TRIM28 expression with the stemness of patient-derived melanoma samples and evaluated potential value for TRIM28 in predicting stem-like phenotype." (PMID 33076560, 2020). "Using the sphere-forming assay as a gold standard assay to assess cancer cell stemness in vitro, we confirmed a role for TRIM28 in facilitating the stem cell-like phenotype of melanoma cells." (PMID 33076560, 2020).
melanoma (continued). "Using a panel of melanoma cell lines, we observed that TRIM28 high expressing cells possess greater melanosphere formation potential, which is reflective of stem cell phenotype." (PMID 33076560, 2020). "First, we compared the expression of TRIM28 on mRNA and protein level and discriminated three groups of melanoma cell lines: low (WM115, WM266, WM3211), medium (SK-MEL28, MEWO), and high (WM9, A375) expressing cell lines." (PMID 33076560, 2020). "In SK-MEL28, WM9, and A375 melanoma cell lines with downregulated TRIM28 expression, the sphere formation was significantly reduced." (PMID 33076560, 2020). "In this study, we found that expression of MAGEC2 protein in tumor cells depends on the expression of TRIM28, a reduction in the level of endogenous TRIM28 expression in melanoma cells resulting in significantly decreased expression of MAGEC2 protein." (PMID 30309319, 2018). "Previous studies have shown that TRIM28 was overexpressed in both liver and peritoneal metastases from patients with colorectal adenocarcinoma, melanoma and malignant thyroid tumors." (PMID 28851455, 2017). "However, in melanoma, TRIM28 upregulates the sensitivity of melanoma cells to targeted BRAF therapy by promoting the degradation of BCL2A1." (PMID 39100077, 2024). "These regulatory phenomena have important consequences in melanoma treatment, where either TRIM28 overexpression or TRIM17 knockout lowers BCL2A1 protein levels and restores melanoma cell susceptibility to B-Raf protooncogene and serine/threonine kinase (BRAF)-directed therapy." (PMID 38225560, 2024). "Melanoma with high TRIM28 expression was also significantly enriched c-Myc-related gene markers." (PMID 36756159, 2023). "In conclusion, our results demonstrate that a TRIM28–JUNB axis controls the balance between invasiveness and growth in melanoma tumors and suggest that the bromodomain protein TRIM28 could be targeted to reduce tumor spread." (PMID 36341538, 2023). "In addition, TRIM28 protein has also been reported to regulate the stem cell-like phenotype of melanoma." (PMID 36756159, 2023). "Melanoma cell lines with high TRIM28 expression were more likely to form melano-sphere." (PMID 36756159, 2023). "Moreover, IRF transcription factor family members (IRF1, IRF2, IRF5, IRF8) were significantly down-regulated in melanoma with high TRIM28 expression, which corresponded to the weakening of interferon signaling." (PMID 36756159, 2023). "Consistently, TRIM28 knockout in melanomas was sufficient to activate immune infiltration." (PMID 35142083, 2022). "However, further studies are needed to precisely define the mechanism of TRIM28-mediated acquisition of stem-like melanoma phenotype." (PMID 33076560, 2020). "Interestingly, the expression of other close-related TRIM family members’ (namely, TRIM24, TRIM33, and TRIM66) does not correlate with the survival of melanoma patients, suggesting that TRIM28 is specifically involved in melanoma progression." (PMID 33076560, 2020). "TRIM28 may serve as a good predictor, efficiently discriminating the “stemness high/immune low” melanoma phenotype." (PMID 33076560, 2020). "Our results indicate that TRIM28 might facilitate the “stemness high/immune low” melanoma phenotype by attenuating interferon signaling leading to a worse prognosis for melanoma patients." (PMID 33076560, 2020). "Enhanced IRF1 promoter methylation observed in TRIM28HIGH expressing melanoma patients is in line with the previous report, although further studies are needed to prove the versatility of TRIM28-mediated repression of other IRF members in “stemness high/immune low” melanomas." (PMID 33076560, 2020). "To conclude, our data indicate that TRIM28 high expression might facilitate “stemness high/immune low” melanoma phenotype by the attenuation of interferon signaling (leading to a worse prognosis for melanoma patients)." (PMID 33076560, 2020).
melanoma (continued). "Melanoma StemnessHIGH patients are characterized with worse prognosis (p < 0.0001) and TRIM28 expression significantly predicts the classification to “stemness high” cohort, either discriminated with the Ben–Porath ES core signature (p < 0.0001) or other stem-cell associated gene signatures." (PMID 33076560, 2020). "Moreover, using shRNA-mediated targeting of TRIM28 in three melanoma cell lines, we confirmed the involvement of TRIM28 in cancer stem cell maintenance." (PMID 33076560, 2020). "Indeed, the expression of stemness markers was lowered in TRIM28-depleted melanoma cells, which strongly supports TRIM28-mediated acquisition of stem cell-like phenotype in cancer." (PMID 33076560, 2020). "It would be critical to determine whether there is a role for TRIM28 in attenuation of immune cell infiltration, or rather TRIM28 is a mediator of the “immune cold” phenotype of melanomas." (PMID 33076560, 2020). "Furthermore, using shRNA-mediated depletion of TRIM28 expression in melanoma cell lines in vitro, we confirmed the TRIM28-mediated repression of IRF family members." (PMID 33076560, 2020). "Moreover, we revealed TRIM28 as a direct mediator of a low antitumor immune response in high stemness melanomas." (PMID 33076560, 2020). "Furthermore, we aimed to evaluate potential value for TRIM28 in predicting stem-like melanoma phenotype." (PMID 33076560, 2020). "In addition, the interaction between endogenous MAGEC2 and TRIM28 was also detected in another human melanoma cell line Hs 695 T." (PMID 30309319, 2018). "However, TRIM28 can positively regulate the abundance of MAGE proteins in melanoma cells." (PMID 39100077, 2024). "However, further studies are needed to determine whether the attenuation of interferon signaling mediated by TRIM28 is sufficient to acquire the stem cell-like phenotype in melanoma." (PMID 33076560, 2020). "Furthermore, TRIM28 emerged as a good predictor of “stemness high/immune low” melanoma phenotype." (PMID 33076560, 2020). "Moreover, it should be clarified whether IRF family members’ repression mediated by TRIM28 is sufficient for the acquisition of stem-cell like phenotype in melanoma." (PMID 33076560, 2020). "Moreover, TRIM28 expression emerged as a good predictor of stem cell-associated melanoma phenotype, regardless of the stemness quantifier." (PMID 33076560, 2020). "TRIM17 and TRIM28 are identified as antagonistic regulators that maintain the balance of BCL2A2 protein levels, thereby modulating melanoma progression." (PMID 41315179, 2025). "TRIM28 depletion therefore leads to higher JUNB expression followed by increased melanoma growth and decreased melanoma invasiveness." (PMID 36341538, 2023). "TRIM17 augments BRAF-targeted therapy sensitivity of melanoma cells by preventing BCL2A1 from being ubiquitinated and degraded by TRIM28." (PMID 35832194, 2022). "For example, TRIM17 binds to BCL2A1 and prevents TRIM28-mediated ubiquitination and degradation of BCL2A1 in melanoma cells." (PMID 33966039, 2021). "Of the other six significant genes identified in the screen (TRIM28, CDYL2, DMAP1, CBX5, PYGO2), TRIM28 is known to increase melanoma tumor propagation potential." (PMID 33527896, 2021). "In melanoma, MAGE-C2 binds to TRIM28 to facilitate TRIM28-Ser824 phosphorylation and sufficient DNA repair in an ATM-dependent manner." (PMID 32731534, 2020). "TRIM28 emerged as a regulator of IRF expression, mediating epigenetic repression of IRF family members in stemness-high melanomas." (PMID 33076560, 2020). "We demonstrate that MAGEC2 interacts with TRIM28 in melanoma cells and MAGEC2 expression in tumor cells depends on the expression of TRIM28." (PMID 30309319, 2018).
melanoma (continued). "Using a combination of data mining, functional perturbations, protein interactome analysis, and in vivo tumor engraftment, we have identified new roles for the bromodomain protein TRIM28, and the transcription factor JUNB, in controlling melanoma growth and metastasis." (PMID 36341538, 2023). "TRIM28 emerged as a regulator Interferon Regulatory Factor family of transcription factors’ expression, mediating epigenetic repression of IRF family members in “stemness high/immune low” melanomas." (PMID 33076560, 2020). "Specifically, TRIM28 high expression correlated with significant depletion of interferon alpha (IFN-α) and interferon gamma (IFN-γ) response in melanomas, which resulted from significant downregulation of IRF (Interferon Regulatory Factor) transcription factor family members." (PMID 33076560, 2020). "We also observed that TRIM28 is a great classification predictor in melanoma patients (either StemnessHIGH/ImmuneLOW or not) with the area under the curve (AUC) equal to 0.7131 as determined with the ROC analysis (p < 0.0001)." (PMID 33076560, 2020). "To identify whether TRIM24HIGH, TRIM33HIGH, or TRIM66HIGH melanoma phenotype reflected the one observed in TRIM28HIGH expressing melanomas, we searched for genes that correlate with the expression of TRIM24, TRIM33, TRIM66, and TRIM28 in SKCM TCGA data." (PMID 33076560, 2020). "Indeed, TRIM28-depleted melanospheres expressed lower levels of stem cell markers, namely OCT-3/4 and SOX2, further supporting our observation of TRIM28-dependant regulation of stem-cell like population in melanoma." (PMID 33076560, 2020). "As TRIM28 downregulation did not affect melanoma proliferation, we suggest that it might attenuate the maintenance of stem cell-like population; therefore, resulting in smaller sizes of melanospheres." (PMID 33076560, 2020). "To determine whether TRIM28 expression is regulated by MACEC2 expression in tumor cells, we also detected the expression level of TRIM28 in MAGEC2-knockdown melanoma cells and no change was observed, suggesting that TRIM28 expression level is not regulated by MAGEC2." (PMID 30309319, 2018).
hepatocellular carcinoma (21 papers, 2012 to 2024). A malignant tumor that arises from hepatocytes. "Higher TRIM28 gene expression has been linked to breast cancer, hepatocellular carcinoma (HCC), and prostate tumors." (PMID 31137886, 2019). "Hepatocellular carcinoma is prevented from progressing by HDAC6 through the formation of a transcriptional repression complex with TRIM28." (PMID 39534556, 2024). "TRIM28 expression correlates with poor prognoses in patients with glioma, hepatocellular carcinoma, ovarian cancer, and early-stage non-small cell lung cancer." (PMID 36077272, 2022). "It has been reported previously that TRIM28 functions as an E3 ligase of FBP1 in Hepatocellular carcinoma." (PMID 30201002, 2018). "Immunohistochemistry (IHC) staining was performed in hepatocellular carcinoma patients to evaluate the association between the expression of MAGEC2 and TRIM28." (PMID 30309319, 2018). "In addition, TRIM28 overexpression was also a predictor for poor prognosis of ovarian cancer, hepatocellular carcinoma and thyroid carcinomas patients." (PMID 30484263, 2019). "Furthermore, expression levels of MAGEC2 and TRIM28 are positively correlated in MAGEC2-positive human hepatocellular carcinoma tissues (p = 0.0011)." (PMID 30309319, 2018). "UBE2S, overexpressed in hepatocellular carcinoma(HCC), interacted with TRIM28 in the nucleus to jointly enhance the ubiquitination of p27 and promoted its degradation and cell cycle progression." (PMID 36756159, 2023). "TRIM28 is often overexpressed in cancer; however, its expression has been shown to be predictive of tumor class in human glioblastomas, and positively correlated with tumor size and development stage, whilst being negatively correlated with patient survival in human hepatocellular carcinoma." (PMID 34579650, 2021). "We detected the expression of MAGEC2 and TRIM28 in human hepatocellular carcinoma (HCC) as MAGEC2 was reported to be more frequently overexpressed in HCC tissues." (PMID 30309319, 2018). "The findings of the study indicate that in the nucleus, overexpression of TRIM28 and UBE2S facilitates p27 ubiquitination, thereby promoting the G1/S phase transition of hepatocellular carcinoma cells and ultimately leading to cell cycle progression." (PMID 38312603, 2024). "UBE2S, which is found to be overexpressed in hepatocellular carcinoma (HCC), interacts with TRIM28 in the nucleus, together promoting the ubiquitination of P27." (PMID 39534556, 2024). "Moreover, UBE2S is highly expressed in hepatocellular carcinoma (HCC), where it interacts with TRIM28 and enhances ubiquitination of p27, thus promoting HCC progression." (PMID 34123793, 2021). "Distribution of TRIM28 expression level in MAGEC2-positive and MAGEC2-negative tissues of hepatocellular carcinoma patients." (PMID 30309319, 2018). "Human hepatocellular carcinoma tissues were immunohistochemically stained with anti-MAGEC2 or anti-TRIM28 antibodies, and H score was assigned to each sample for MAGEC2 and TRIM28, respectively." (PMID 30309319, 2018). "High expression of TRIM28 increased glucose consumption and lactate production by promoting FBP1 degradation in hepatocellular carcinoma and resulted in stimulation of cancer cells growth both in vitro and in mice model." (PMID 28851455, 2017). "Furthermore, both the mRNA and protein level of TRIM28 were significantly higher in tumor tissues than in adjacent normal tissues in hepatocellular carcinoma patients (HCC)." (PMID 28851455, 2017). "Notably, TRIM-28 and -33 form a multiprotein complex together with TRIM-24 that has been shown to act as tumor suppressor, for example, in the context of hepatocellular carcinoma." (PMID 25755299, 2015). "However, recent studies showed that loss of TRIM24 in mice led to hepatocellular carcinoma development and TRIM24 interacted with TRIM28 and TRIM33 to form regulatory complexes that suppressed murine hepatocellular carcinoma, suggesting its role as a tumor suppressor in heptocellular carcinoma." (PMID 22666376, 2012).
hepatocellular carcinoma (continued). "Contrastingly, TRIM24 was reported to act as a tumour suppressor in murine hepatocellular carcinoma (HCC) by dysregulating retinoic acid receptor (RAR) signalling, and it was later shown that TRIM24, TRIM28 and TRIM33 can form regulatory complexes to suppress murine HCC." (PMID 32731534, 2020).